ENSG00000201957
Synonyms: LOC124900560
Gene: Small nucleolar RNA gene on chromosome 3 (179,169,083 to 179,169,210, reverse strand). Ensembl gene ENSG00000201957.
Gene Ontology:
Biological process: RNA processing
Cellular component: nucleolus
Homologues: Paralogues in human: SNORA25 (84% identical), SNORA25B (81% identical).